ERBB2 (erb-b2 receptor tyrosine kinase 2)
Diseases named in the same sentence as ERBB2 in open-access papers (continued):
Sharing a sentence is not in itself a finding about the gene and the disease.
breast cancer (continued). "We showed that overexpression of erbB3 upregulated Survivin to confer paclitaxel resistance in erbB2-overexpressing breast cancer cells." (PMID 27177222, 2016). "In the clinic, trastuzumab, pertuzumab, lapatinib, and TDM-1 have been used in anti-HER2 therapy for ERBB2-overexpressing breast cancer." (PMID 26907936, 2016). "We have previously demonstrated that the overexpression of the p130Cas adaptor protein in ErbB2 positive breast cancer, promotes tumor aggressiveness and progression." (PMID 26716506, 2016). "In a first step, we checked the protein levels of the single ERM proteins in SKBR3 breast cancer cells, which express high levels of ErbB2." (PMID 27029001, 2016). "EGFR mutations are indeed major drivers of cancer progression, and ErbB2 amplification is a common oncogenic event in breast cancer." (PMID 27351228, 2016). "The oncogenic receptor tyrosine kinase ErbB2, overexpressed in over 20% of breast cancers, has served as a major target for the development of targeted drug delivery strategies." (PMID 26859680, 2016). "Lapatinib, a tyrosine kinase inhibitor (TKI) of EGFR and ErbB2, and trastuzumab, an anti-ErbB2 antibody, are used for treatment of breast cancers and some gastric cancers." (PMID 27531070, 2016). "In trastuzumab-sensitive breast cancer cells, both trastuzumab and pertuzumab block ErbB2 dimerization and inhibit the activation of the main downstream pathways of ErbB2: PI3K/AKT and MAPK/ERK signaling pathways." (PMID 27564098, 2016). "Approximately 15%–20% of breast cancers have amplification of the ERBB2 gene, which codes for HER2 (human epidermal growth factor receptor 2) on chromosome 17." (PMID 27556700, 2016). "Using a similar approach, same authors also developed other amperometric magnetoimmunosensor for the breast cancer biomarker ErbB2." (PMID 27681733, 2016). "Herceptin (trastuzumab) is a humanised monoclonal antibody that specifically targets HER2 (EGFR-2/ERBB2), which is overexpressed in approximately 20% of breast cancers." (PMID 27543060, 2016). "This is supported by the observation that over-activation of AKT drives initiation of tumorigenesis but inhibits invasion and metastasis in an ERBB-2-induced mammary tumor model." (PMID 27515171, 2016). "As a dual tyrosine kinase inhibitor against both EGFR and erbB2, lapatinib has been approved to treat the erbB2-positive breast cancer patients that have progressed on trastuzumab-based regimens." (PMID 26621843, 2016). "We have previously demonstrated that alcohol increases intracellular ROS accumulation in breast cancer cells and plays a role in alcohol-induced ErbB2 activation." (PMID 27416801, 2016). "More importantly, down-regulation of p38γ MAPK by shRNA significantly inhibits alcohol-induced increases in CSC population, mammosphere formation and migration/invasion of breast cancer cells overexpressing ErbB2." (PMID 27416801, 2016). "These experiments confirmed the ability of Trast-NG to deliver chemotherapeutic payloads to ErbB2-overexpressing breast cancer cells with high specificity." (PMID 26859680, 2016). "Our data show, in a conditional mouse model, that the glucose transporter GLUT1 is required for the formation of mammary tumors and for robust ERBB2-induced proliferation in a 3D model of malignant transformation." (PMID 27998284, 2016). "ERBB2 oncogenic potential and cell surface availability have led to the development of targeted anti-ERBB2 antibodies, such as trastuzumab (Herceptin) that has become the standard care for patients with ERBB2-positive breast cancer." (PMID 26899482, 2016).
breast cancer (continued). "Our data provide a basis for rational design of novel effective combinatorial regimens to overcome resistance and thereby improve the survival of breast cancer patients whose tumors overexpress erbB2 and become resistant to erbB2-targeted therapy." (PMID 26621843, 2016). "Accordingly, it is important to develop new breast cancer therapies based on the combination of Hh pathway inhibitors and ErbB2, EGFR, Wnt and Notch signaling inhibitors." (PMID 26843616, 2016). "Together, our findings provide novel insights into the role of HSP90 in ERBB2 processing, and of the molecular mechanisms underlying HSP90 inhibition in SKBR3 breast cancer cells." (PMID 27863425, 2016). "Such cross-talk activation of ERBB2/HER2 signalling was identified as an alternate route in the upregulation of PRLR induced by its cognate hormone in breast cancer cells." (PMID 27564112, 2016). "Genes with recurrent amplifications in breast cancer showed 100% (ERBB2, FGFR1), 96% (CCND1), and 88% (MYC) concordance for the amplified/non-amplified status." (PMID 27028851, 2016). "Overexpression of ERBB2 in breast cancers correlates with a poor prognosis due to enhanced metastatic potential and resistance to chemotherapy." (PMID 27863425, 2016). "They represent approximately 20% all breast cancer cases and harbor Erbb2 gene amplification, resulting in greater than normal amounts of the HER-2 protein." (PMID 27902734, 2016). "HER2 (ErbB2 or NEU), a member of the ErbB family of receptor tyrosine kinases (RTKs), is the main pathogenic gene in breast cancer; HER2 overexpression has been demonstrated in 20 to 30% of patients." (PMID 27363028, 2016). "This is the first application of these parameters in cases with neoadjuvant treatment of ERBB2-positive breast cancer." (PMID 27576528, 2016). "EGFR mutations and ERBB2 overexpression are well known mechanisms that lead to constitutive activation of ERBB signaling pathways in lung and breast carcinoma." (PMID 26745281, 2016). "Trastuzumab (Herceptin), a humanized antibody, is in clinical use for ErbB2-positive breast carcinoma." (PMID 27894092, 2016). "Triple-negative breast cancers (TNBCs), lacking estrogen receptor (ER), progesterone receptor, and ERBB2 (also known as HER-2/neu), are more aggressive and difficult to treat than other subtypes of breast cancers." (PMID 26219228, 2015). "More recently, we showed that MCF-10A cells overexpressing ERBB2 and ERBB2-positive breast cancer cells stabilizes HIF-1α levels and that HIF-1α is required for ERBB2 oncogenesis in vivo and anoikis resistance in vitro." (PMID 25596742, 2015). "Decrease in ShcA levels or conversely the expression of a dominant-negative ShcA mutant lead to the blocking of motility induced by TGF-β and furthermore also leads to the inhibition of invasion of Neu/ErbB2- expressing breast cancer cells." (PMID 25890053, 2015). "Of note, breast cancer cells treated with the anti-ERBB2 moAb trastuzumab have an activation of EGFR signalling as a mechanism of acquired resistance." (PMID 26318427, 2015). "In breast cancer, ErbB2/HER2 is found to be amplified and/or overexpressed in up to 30% of patients, correlating with poor prognosis." (PMID 25630670, 2015). "To address a role for EIS in carcinogenesis, we analyzed ERBB2-positive breast cancer and normal breast tissues (NBS)." (PMID 25934563, 2015). "HRG signaling was also negatively affected by miR-149 and miR-520a-3p expression in SKBR3 cells, a breast cancer cell line with ErbB2 amplification." (PMID 25630670, 2015). "Several studies with human tumor cell lines have suggested PTK6 contributes to ERBB2-induced breast cancer." (PMID 26247733, 2015). "In ERBB2-overexpressing breast cancer cells, beta-catenin co-activates AR to drive transcription of several tumor-promoting targets, including ERBB3 {{}}." (PMID 26509276, 2015).
breast cancer (continued). "Here, we show that hypoxia, via HIF-1, induces resistance to lapatinib-mediated effects in ERBB2-expressing mammary epithelial and ERBB2-positive breast cancer cells." (PMID 25596742, 2015). "We investigated the frequency of six known breast cancer amplicons excluding 17q12 (ERBB2), and all of them were frequently detected in grade III tumors as genomic gains." (PMID 25391423, 2015). "Such is the case in breast cancer, where the human epidermal growth factor receptor 2 (Her2/ErbB2) protein found on normal breast tissue is upregulated in 15 to 30% of breast cancers." (PMID 26334628, 2015). "It has been demonstrated that β-catenin activation is critical for tumorigenesis in an ErbB2/HER2-mediated mouse mammary tumor model." (PMID 26268703, 2015). "For the first time, we showed that PDL1 was differentially expressed across the major breast cancer molecular subtypes, with more frequent upregulation in basal and ERBB2-enriched subtypes than in luminal A, luminal B and normal-like subtypes." (PMID 25669979, 2015). "Activation of these pathways through hetero-dimerization of erbB2 and erbB3 can lead to multi-drug resistance in breast cancers." (PMID 26703550, 2015). "Here, for the first time we differentiate ERBB2-positive breast cancers according to different pathophenotypes and molecular subphenotypes to evaluate their associations by a systems biology approach." (PMID 25853295, 2015). "ERBB2 is a major gene that determine the molecular subtype of breast cancer and S100A7A has been shown to be down-regulated in estrogen receptor negative tumors." (PMID 26669540, 2015). "On the other hand, GRP94 correlates with ErbB2 expression and poor BrM free survival of breast cancer patients." (PMID 26497551, 2015). "ERBB2/NEU/HER2 (henceforth ERBB2)-positive breast cancers constitute 20 to 30% of all mammary gland tumors." (PMID 25853295, 2015). "Previous studies showed that Cyclin D1 and D3 are overexpressed in human breast cancer cell lines and primary invasive breast cancers and Cyclin D3 frequently exceeded the expression of Cyclin D1 in ErbB2-positive cases." (PMID 26412984, 2015). "They found that the selective inhibition of PPAR-γ, a well-established positive regulator of adipogenesis and lipid storage, leads to a significant decrease of the ALDH+ cell population, specifically in ERBB2+ breast cancer cells." (PMID 26064420, 2015). "More recently, it has been shown that transmembrane domain targeting peptide antagonizing ErbB2/Neu exhibit anticancer properties by inhibiting breast tumor growth and metastasis in genetically engineered mouse model of breast cancer." (PMID 26635612, 2015). "In SK-BR3 cells (breast cancer cells overexpressing ErbB2) treated with the proteasome inhibitor bortezomib, ErbB2 co-immunoprecipitates with a complex containing c-Cbl and USP9X." (PMID 25672900, 2015). "A combination therapy targeting c-MYC and ERBB2 was predicted to improve treatment for breast cancer that is de novo resistant to ERBB2 inhibition." (PMID 25741385, 2015). "Since the genetic background influences the clinical progression of ERBB2-positive breast cancer, we investigated the quantitative trait loci (QTLs) associated with heterogeneous tumor behavior in the F1BX mice by linkage analysis." (PMID 25853295, 2015). "For example, the use of the drug trastuzumab against ERBB2 has been shown to improve breast cancer survival rates alone or in combination with other treatments." (PMID 26273658, 2015). "Concurrently, the overexpression of miR-125a/b was found to reduce ErbB2/3 at both the transcript and protein level in the human breast cancer cell line SKBR3 thereby reducing AKT signaling." (PMID 26544868, 2015). "A recent study reported that both basal-like and claudin-low breast cancers exhibited a high probability of metastasizing to the brain and lung, while ErbB2-enriched tumors preferentially colonized the liver." (PMID 26497551, 2015).
breast cancer (continued). "Here, we demonstrate for the first time that hypoxia promotes lapatinib resistance in ERBB2-positive breast cancer cells through activation of the MEK-ERK pathway in a HIF-1-dependent manner via regulation of DUSP2." (PMID 25596742, 2015). "ErbB2 has oncogenic properties and is found overexpressed in up to 25% of human breast cancers where it is predictive of poor prognosis." (PMID 25875008, 2015). "In particular, in SKBR3 breast cancer cell line, quercetin treatment resulted in a suppression of tyrosine kinase activity and in a reduction of ErbB2/neu protein level as well as in a dephosphorylation of phosphatidylinositol-3-kinase (PI3K) and Akt." (PMID 25918934, 2015). "Overexpression of the receptor tyrosine kinase HER2/neu (ErbB2) in breast cancer, led to increased HIF-1α expression, increased ERK and Akt activities, reduced Bim expression and resistance to anoikis." (PMID 26405162, 2015). "In summary, we have shown that hypoxia promotes lapatinib-resistance in ERBB2-positive breast cancer cells via HIF1-regulation of the ERK pathway." (PMID 25596742, 2015). "Lapatinib, a small molecule kinase inhibitor, blocks both EGFR and ERBB2 kinase activity and is currently used in combination therapy with DNA damaging agents in ERBB2-positive breast cancers." (PMID 25596742, 2015). "In breast cancer, molecular profiling studies have enabled identification of ErbB2-positivebreast cancer molecular subtype, which represents up to 30% of breast cancers." (PMID 25699077, 2015). "Since ERBB2 overexpression in breast cancer cells is critical for tumor progression it is an attractive therapeutic target." (PMID 25596742, 2015). "For example, studies with ERBB2+ breast cancer have shown that targeting multiple alternative kinases upregulated by adaptive kinome reprogramming after the development of resistance to lapatinib increased growth inhibition of tumor cells variably." (PMID 26596901, 2015). "HIF-1α expression predicts poor therapeutic response and clinical outcome in human breast cancers and contributes to resistance to the tyrosine kinase inhibitor Lapatinib in ErbB2-positive breast cancer cells." (PMID 26405162, 2015). "It was reported that the expression of the NH2 terminally truncated ErbB2 (95 kDa) in breast cancer correlated with metastatic disease progression compared with the expression of full-length ErbB2 (185 kDa)." (PMID 26673159, 2015). "Amplification of 17q12–q21 is common in ERBB2 overexpressing breast cancers, particularly in a 280 kb region that includes the 3 additional genes identified above." (PMID 26543765, 2015). "We examined DUSP2 expression in three different ERBB2 expressing breast cancer cell lines and observed that DUSP2 protein levels are downregulated under hypoxic conditions." (PMID 25596742, 2015). "In recent years, ERBB2 has evolved to become an important prognostic biomarker and therapeutic target for breast cancer, and targeted therapies such as HerceptinTM (trastuzumab) and OmnitargTM (pertuzumab) are now available clinically." (PMID 26109171, 2015). "For cancers of the breast, BrM occurs after diagnosis of systemic metastases from tumors belonging to one of two categories: tumors with amplification of ErbB2 or TNBC; the incidence of both exceeds one-third of patients." (PMID 26497551, 2015). "It was also reported that IKKα induces ErbB2 to activate NF-κB through the canonical pathway by enhancing the invasive capacity of ErbB2+ breast cancer cells." (PMID 25918934, 2015). "MiR-125b, which targets erythropoietin (EPO) and its receptor (EPOR) as well as ERBB2, is found to be one of the most downregulated miRNAs in breast cancer." (PMID 25849621, 2015). "Considering simultaneously tumor pathophenotypes and several molecular levels, we show the heterogeneous behavior of ERBB2-positive breast cancer in terms of disease progression." (PMID 25853295, 2015).
breast cancer (continued). "Here, we show that hypoxia promotes lapatinib resistance in ERBB2- expressing breast cancer cells through HIF-1-mediated ERK activation." (PMID 25596742, 2015). "ER, expression of HER2 (erbB2/neu) and histological grade sub classify breast cancers into at least four molecular subtypes." (PMID 26460486, 2015). "Trastuzumab is predominantly used in the treatment of the ErbB2-positive breast cancer subtype where its combination with conventional chemotherapy, had a significant effect on disease free survival of patients with early stage ErbB2+ breast cancer." (PMID 26635612, 2015). "ErbB2-positive (HER2/neu) breast cancer cells are usually treated with lapatinib (a dual inhibitor of the EGRF and ERBB2/HER2 tyrosine kinase inhibitor) as a first line monotherapy." (PMID 25866793, 2015). "The progress with small molecule drugs is mirrored by the successful introduction of protein-based therapeutics, particularly antibodies, as exemplified by the anti- ERBB2 monoclonal antibody trastuzumab in ERBB2-positive breast cancer." (PMID 26613930, 2015). "In total, 25 correlated and four anti-correlated drug sensitivities were revealed of which only one drug, Sirolimus, showed significantly lower IC50 values in the luminal/ERBB2 breast cancer subtype." (PMID 26543746, 2015). "Garcinol has been previously tested in pancreatic cancer and breast cancer, in conjunction with other anti-cancer agents namely gemcitabine, curcumin and anti-ERBB2 antibody." (PMID 25762616, 2015). "Human epidermal growth factor receptor 2 (HER2) overexpression (encoded by the ERBB2 gene) has long been a prognostic marker and predictive tool in the treatment of breast cancer, and more recently in esophagogastric cancer 2,3." (PMID 25720673, 2015). "Breast cancer induced by ERBB2 exhibits a broad and heterogeneous range of clinical progression in different patients." (PMID 25853295, 2015). "Despite its ligand-independent active conformation, ErbB2-induced transformation of breast cancer cells is dependent on ErbB3." (PMID 25630670, 2015). "Lapatinib is a dual tyrosine kinase inhibitor of EGFR and ErbB2/HER2 receptors that is used in combination therapy of ErbB2/HER2-positive breast cancer patients with advanced or metastatic tumors." (PMID 25599599, 2015). "ErbB3-dependent signal transmission relies on the dimerization partner ErbB2, a receptor tyrosine kinase that is frequently overexpressed and/or amplified in breast cancer cells." (PMID 25630670, 2015). "This region also harbors the gene encoding for the tumor suppressor BRCA1, that is altered in 20-30% of breast cancers and most often accompanied by an amplification of ERBB2." (PMID 25622104, 2015). "The ERK5 pathway also appears to play a role in mediating chemoresistance in breast cancer cells and contributes to neuregulin signaling in breast cancer cells overexpressing ErbB2." (PMID 26040563, 2015). "Breast cancer can be separated into five subgroups termed Luminal A, Luminal B, Normal-like, ErbB2 over-expressing and Basal-like." (PMID 26627005, 2015). "Breast cancer patients expressing ErbB2 are treated with humanized monoclonal antibody, trastuzumab." (PMID 26437434, 2015). "Upon activation by Sema4D, Plexin-B1 can interact with the receptor tyrosine kinase (RTK) Met to promote migration in several carcinoma cell lines, and similar synergistic interaction of Plexin-B1 with ErbB2 has been reported in breast cancer cells." (PMID 25762646, 2015). "Trastuzumab, a humanized anti-HER-2 monoclonal antibody, has been approved for treatment of patients with breast cancers that overexpress the human epidermal growth factor receptor-2 (HER-2) protein or that exhibit ErbB2 gene amplification." (PMID 25984950, 2015). "Using this model, we demonstrated an interaction between estrogen and erbB-2 induced mammary tumor development in transgenic mice." (PMID 25853264, 2015).